CARD8 (caspase recruitment domain family member 8)
Diseases named in the same sentence as CARD8 in open-access papers (continued):
Sharing a sentence is not in itself a finding about the gene and the disease.
rheumatoid arthritis (3 papers, 2021 to 2024). A chronic, systemic autoimmune disorder characterized by inflammation in the synovial membranes and articular surfaces. "Therefore, variants in CARD8 related with its lower expression also was associated with autoimmune disorders including rheumatoid arthritis and type 1 diabetes." (PMID 39630946, 2024).
cervical cancer (2 papers, 2015 to 2022). A primary or metastatic malignant neoplasm involving the cervix. "In this study, we therefore hypothesized that CARD8 eQTLs SNPs within lncRNA may influence the risk of HCC and cervical cancer." (PMID 26147888, 2015). "LncRNA AC008392.1 is one of newly identified lncRNAs, which locates in the upstream region of CARD8 in the nineteenth chromosome and is expressed in multiple cell lines such as GM12878 (Human B lymphocyte) and HeLaS3 (Human cervical cancer cells)." (PMID 26147888, 2015). "Caspase recruitment domain family, member 8 (CARD8) can coordinate innate and adaptive immune responses and sensitize cells to apoptosis, which may participate in tumorigenesis of virus-induced hepatocellular carcinoma (HCC) and cervical cancer." (PMID 26147888, 2015).
coronary artery disease (2 papers, 2021 to 2022). "In our study, we found that the CARD8 rs2043211 polymorphism was associated with protection against coronary artery disease." (PMID 36105941, 2022). "First, longitudinal studies are required to explore the role of NLRP3 (rs4612666) and CARD8 (rs2043211) as a therapeutic marker for both periodontitis and coronary heart disease." (PMID 34199122, 2021).
lung carcinoma (2 papers, 2006 to 2026). "This study utilized immunoinformatics and structural bioinformatics approaches to design and evaluate a multi-epitope vaccine targeting pyroptosis-associated antigens (CARD8, NAIP, NLRP1, and NLRP3), which are implicated in lung cancer immunology." (PMID 41857073, 2026).
myocardial infarction (2 papers, 2022 to 2024). Gross necrosis of the myocardium, as a result of interruption of the blood supply to the area, as in coronary thrombosis. "Expression of CARD8 mRNA and protein has been identified in human atherosclerotic lesions, and the truncated T30A variant (rs2043211) of CARD8 has been associated with lower C-reactive (CRP) and MCP-1 levels in myocardial infarction patients." (PMID 38350853, 2024).
tuberculosis (2 papers, 2019 to 2021). A chronic, recurrent infection caused by the bacterium Mycobacterium tuberculosis. "In this context, we have focus on one SNV in the AIM2 inflammasome in tuberculosis together with two other SNVs, one in CARD8 and one in CTSB, that are related to NLRP3 pathway." (PMID 33868225, 2021).
Atherosclerotic lesion (1 paper, 2024). A lesion associated with atherosclerosis, a multifactorial and multipart progressive disease manifested by the focal development within the arterial wall of lesions, that ranges from the development of a fatty streak, plaque progression, and plaque disruption. "We have also identified that CARD8 acts as a regulator of inflammatory cytokines and chemokines like CXCL1, CXCL6, PDGF-A, MCP-1 and IL-6 in endothelial cells and atherosclerotic lesions, which indicates that CARD8 plays an important role for the regulation of proteins involved in inflammation." (PMID 38350853, 2024).
Autoimmunity (1 paper, 2021). The occurrence of an immune reaction against the organism's own cells or tissues. "Additionally, inflammasomes play a vital role in the development and progression of autoimmunity, inflammation and metabolic disease, and many SNPs in inflammasome-associated genes, including NLRP1, NLRP3, NLRP12 and CARD8, are involved in and associated with patient susceptibility to T1DM." (PMID 34867336, 2021).
breast carcinoma (1 paper, 2014). "CARD8, located at 19q13, encodes the caspase recruitment domain protein 8 (CARD8), also known as TUCAN, which has been reported to interact with NLRP3, suppress NF-κB activating signals and be overexpressed in human cancer tissues including ovarian, lung and breast cancer tissues." (PMID 24901306, 2014).
cervical tumor (1 paper, 2015). "Given that the findings from our previous study, we hypothesized that lncRNA AC008392.1 might regulate the expression of related protein (CARD8) by itself variation and thereby influence the occurrence and development of hepatic tumor and cervical tumor." (PMID 26147888, 2015).
chronic myeloid leukemia (1 paper, 2018). "Similar results were also observed in chronic myeloid leukemia (CML) patients in which genotyping demonstrated that genetic polymorphisms of IL-1β-rs16944, IL-18-rs1946518, and CARD8-rs2043211 were associated with the pathophysiological characteristics and treatment of CML patients." (PMID 30447690, 2018).
cryopyrin-associated periodic syndrome (1 paper, 2024). Cryopyrin associated periodic syndrome (CAPS) defines a group of autoinflammatory diseases, characterized by recurrent episodes of systemic inflammatory attacks in the absence of infection or autoimmune disease. "Gain-of-function mutants of NLRP3, which are the cause of the auto-inflammatory disorder cryopyrin-associated periodic syndrome (CAPS), cannot interact with CARD8, suggesting that the lack of NLRP3 inhibition by CARD8 is the reason for the inflammatory phenotype in CAPS patients." (PMID 38920661, 2024).
epilepsy (1 paper, 2021). A brain disorder characterized by episodes of abnormally increased neuronal discharge resulting in transient episodes of sensory or motor neurological dysfunction, or psychic dysfunction. "Carriers of at least one polymorphic IL1B rs16944 allele were more likely to develop epilepsy only when carrying at least one polymorphic CARD8 rs2043211, further emphasizing the important role of CARD8-IL1B gene–gene interaction." (PMID 34573127, 2021). "In our study, carriers of at least one polymorphic CARD8 rs2043211 allele were less likely to develop epilepsy only in carriers of two normal IL1B rs16944 or rs1143623 alleles." (PMID 34573127, 2021). "CARD8 rs2043211 was associated with lower epilepsy risk, while IL1B rs16944 was associated with higher epilepsy risk, (when stratified for IL1B rs16944 or CARD8 rs2043211 genotype, respectively)." (PMID 34573127, 2021).
hepatitis C (1 paper, 2021). "In the present study, we analyzed whether polymorphisms in inflammasomes genes IL1B rs16944, IL18 rs187238, NLRP3 rs10754558, CARD8 rs2009373, CTSB rs1692816 and AIM2 rs1103577 are associated with susceptibility to HCV infection and liver fibrosis in hepatitis C patients in the Amazon population." (PMID 34161370, 2021). "Gene-gene interaction showed that individuals heterozygotes for both CARD8 rs2009373 and IL1B rs16944 are less prone to hepatitis C development (padj = 0.039)." (PMID 34161370, 2021).
lung adenocarcinoma (1 paper, 2024). A carcinoma that arises from the lung and is characterized by the presence of malignant glandular epithelial cells.
malignant melanoma (1 paper, 2017). "We have identified 4 inflammasome related Single Nucleotide Polymorphisms (SNPs) for CARD8 (rs6509365); IL1B (rs1143643) and IL18 (rs5744256 and rs1834481) related to melanoma susceptibility/protection." (PMID 27942564, 2017).
myeloid leukemia (1 paper, 2020). A clonal proliferation of myeloid cells and their precursors in the bone marrow, peripheral blood, and spleen. "Recently, CARD8 was identified as a novel inflammasome sensor that triggers pyroptosis in myeloid leukemia cells upon inhibition of dipeptidyl‐peptidases (DPP)." (PMID 32840892, 2020).
myocarditis (1 paper, 2023). Myocarditis is a condition that is characterized by inflammation of the heart muscle (myocardium). "The collection of evidence demonstrates that CVB3-induced myocarditis can impair cardiac function by cleaving host proteins involved in the immune response, including MAVs, TRIF, NFAT5, SQSTM1, and CARD8, to impair host defense mechanisms and promote pyroptosis and apoptosis." (PMID 37175422, 2023).
infection (11 papers, 2018 to 2025). The state of being infected such as from the introduction of a foreign agent such as serum, vaccine, antigenic substance or organism. "Infection with SFTSV led to reduction of NLRP1/CARD8 NT and MG132 restored NLRP1 NT, indicating that N-terminal functional degradation occurs in a proteasome-dependent manner during activation of the NLRP1 and CARD8 inflammasome." (PMID 40608794, 2025). "We demonstrate that cell-to-cell transmission of HIV-1 from T cells to myeloid cells in both immortalized and primary cell coculture models of infection yields CARD8-dependent inflammasome activation via incoming HIVPR." (PMID 39229127, 2025). "HIV-1Q23-BG505 infection also resulted in IL-1β secretion in a CARD8-dependent manner, suggesting that CARD8-dependent inflammasome activation is conserved across HIV-1 strains." (PMID 37417868, 2023). "Unexpectedly, we revealed a statistically significant, CARD8-dependent increase in IL-1β as early as 2 hr after infection (the first timepoint assayed after the initial infection), which plateaued for the next 6 hr and then further increased by 24 hr post-infection." (PMID 37417868, 2023). "Taken together, our data indicate that CARD8 plays a pivotal role in sensing and responding to HIV-1 cell-to-cell infection between primary CD4 T cells and macrophages." (PMID 39229127, 2025). "We next infected both WT, CARD8 KO, or CASP1 KO THP-1 cells with WT HIV-1LAI or HIV-1LAI-VSVG viruses at an MOI that would give 30–50% infection of WT cells." (PMID 37417868, 2023). "In contrast, infection with both VSV-g pseudotyped and replication competent HIV-1LAI induced IL-1β secretion and cell death only in CARD8 KO THP-1 cells that were complemented with WT human CARD8, but not CARD8 mutants that are resistant to HIV-1PR cleavage." (PMID 37417868, 2023). "However, as HIV-1 triggers CARD8 inflammasome activation as early as 2 hr post-infection, well before de novo synthesis of viral proteins, our findings suggest that HIV-1 entry is also targeted by CARD8 via the innate immune detection of incoming viral protease activity." (PMID 37417868, 2023). "Thus, genetic polymorphisms in innate immunity-related genes such as CARD8 and NLRP3 may contribute to the understanding of why most exposed individuals do not develop infection." (PMID 30816317, 2019).
cancer (6 papers, 2014 to 2022). A tumor composed of atypical neoplastic, often pleomorphic cells that invade other tissues. "For example, VbP induces CARD8‐mediated pyroptosis in AML cells in vivo, slowing cancer progression." (PMID 32558991, 2020). "Thus, the anti‐cancer potential of NLRP1 and CARD8 inflammasome activation also warrants further study." (PMID 32558991, 2020).
tumor (6 papers, 2006 to 2025). "Four tumor pyroptosis-associated antigens, CARD8, NAIP, NLRP1, and NLRP3, were screened as potential candidates for LUAD mRNA vaccine development." (PMID 38166691, 2024). "The antigens CARD8, NAIP, NLRP1, and NLRP3, which are associated with tumor pyroptosis, could be candidate molecules for LUAD mRNA vaccine development." (PMID 38166691, 2024). "CARD8 may affect the progress of tumor biology by inhibiting cell apoptosis and participating in the NFkB signaling pathway." (PMID 35814404, 2022).
infectious disease (2 papers, 2016 to 2019). A disorder directly resulting from the presence and activity of a microbial, viral, or parasitic agent in humans. "A comparison of CARD8 genes among different mammalian populations suggested that the increase in infectious disease burden associated with animals that live in herds or colonies may have naturally selected for loss of CARD8 multiple times in mammalian evolution." (PMID 27128945, 2016).
metabolic disease (2 papers, 2021 to 2022). A congenital disorder (due to inherited enzyme abnormality) or acquired (due to failure of a metabolically important organ) disorder resulting from an abnormal metabolic process. "Other inflammasomes and molecules related to the activation cascade (e.g., CARD8, AIM2, IFI16, CASP-1, and IL-1β) have also been found to be associated with a variety of infections and metabolic diseases." (PMID 36105941, 2022).
heart disease (1 paper, 2021). "We focused on the relationship between the two biomolecules namely NLRP3 (rs4612666) and CARD8 (rs2043211) with gum and heart disease." (PMID 34199122, 2021).
CARD8 also shares sentences with these, for which no sentence is quoted: leukemia (3 papers); AIDS (1); aneurysm (1); angina pectoris (1); arterial hypertension (1); autoimmune disease (1); bacterial meningitis (1); chronic hepatitis C (1); chronic kidney disease (1); chronic periodontitis (1); coinfection (1); colorectal cancer (1); fibrosis (1); hepatocellular carcinoma (1); inflammatory bowel disease (1); ischemic stroke (1); non-small cell lung carcinoma (1); periodontitis (1); pulmonary TB (1); Splenomegaly (1); Stroke (1); transient ischemic attack (1); type 1 diabetes (1).